FAAH (fatty acid amide hydrolase)
Diseases named in the same sentence as FAAH in open-access papers (continued):
Sharing a sentence is not in itself a finding about the gene and the disease.
Anxiety (continued). "Whether this finding suggests a less efficacious anxiolytic-like potential of SSR411298 compared with benzodiazepines, or indicates that the FAAH inhibitor may have a different spectrum of therapeutic activity in anxiety conditions than benzodiazepines, remains to be verified." (PMID 29403000, 2018). "Furthermore, previous associations between variation in CNR1 and FAAH and fear extinction have been observed in response to short‐term experimentally conditioned fears in adults and not to clinical levels of anxiety in children and adolescents." (PMID 27346075, 2017). "Thus, pharmacological inhibition of FAAH might be a viable pharmacological strategy for the treatment of anxiety-related cardiac dysfunction." (PMID 26656183, 2015). "Thus, the fact that a reduction of anxiety-like behaviors in Ts65Dn mice could only be achieved with JZL184 doses that increased brain levels of AEA is consistent with a mechanism requiring FAAH inhibition." (PMID 25474204, 2014). "In the next step, we used inhibitors of enzymes that break down endocannabinoids in the brain (FAAH inhibitor URB 597 and MAGL inhibitor JZL 184) to evaluate the indirect impact of the ECS on the anxiety behavior in mice." (PMID 40005177, 2025). "Preclinical and early clinical findings suggest that cannabinoids—particularly CBD—and enzymatic inhibitors of the endocannabinoid system, such as FAAH and MAGL inhibitors, hold significant therapeutic potential for anxiety and depressive disorders." (PMID 41471306, 2025). "Pharmacological agents, including CB1R agonists, monoacylglycerol lipase (MAGL) inhibitors (for 2-AG), and fatty acid amide hydrolase (FAAH) inhibitors (for AEA), have demonstrated efficacy in alleviating headache and anxiety-related behaviors." (PMID 41377021, 2025). "The other group consists of inhibitors of enzymes degrading AEA (fatty acid amide hydrolase—FAAH) and 2-AG (monoacyloglycerol lipase—MAGL) being explored for their potential in treating anxiety and pain." (PMID 40283681, 2025). "Modulating this axis, through inhibitors of FAAH, TRPV1, and MAGL holds potential for sociability impairments, depression and anxiety." (PMID 40605060, 2025). "For instance, CRH, by activating the CRH1 type receptor, leads to rapid FAAH production, driving AEA hydrolysis in the amygdala and ultimately leading to anxiety-like behavior." (PMID 38685914, 2024). "FAAH is responsible for degrading AEA, and its gene deletion results in increased AEA content in the brain, leading to an improvement in anxiety-like behavior." (PMID 38685914, 2024). "Interestingly however, once participants were stratified based on whether their trough levels of AEA were increased, it was found that those who exhibited the largest increases in AEA following treatment with the FAAH inhibitor also exhibited the greatest reduction in anxiety symptoms." (PMID 37671673, 2023). "Under stress exposure conditions, the protein FAAH is mobilized to degrade the AEA, therefore increasing the neuronal excitability in the amygdala, a key anxiety-mediating region of the brain." (PMID 36101457, 2022). "Further clinical evidence shows that administration of FAAH inhibitors decreases amygdala BOLD reactivity to threatening stimuli in healthy males, indicating a potential marker for decreased stress and anxiety." (PMID 37235067, 2022). "A relevant sex difference has been previously demonstrated with the FAAH inhibitor URB597, which was less able to reduce anxiety-like symptoms in female rats exposed to chronic unpredictable stress compared to male rats." (PMID 36291671, 2022). "The inhibition of FAAH, the key enzyme responsible for the deactivation of this fatty acid, could therefore offer a treatment strategy for several neuropsychiatric and neurological diseases, including chronic pain, inflammation, neurodegeneration, depression, anxiety." (PMID 35056095, 2021).
Anxiety (continued). "To determine if the elevated FAAH activity and reduced AEA levels contributed to the increase in anxiety-like behavior, we examined if acute inhibition of FAAH, to elevate AEA signaling, would counter the colitis-induced anxiety." (PMID 33452437, 2021). "FAAH inhibition and the consequent increase of AEA in the brain regions involved in the regulation of stress and anxiety seem to restore dysfunctional homeostasis of AEA signaling because of stress exposure." (PMID 32395111, 2020). "It is quite evident from this experiment that FAAH inhibition declines AEA degradation, which via CB1 modulation decreases anxiety-like behaviors." (PMID 33066366, 2020). "FAAH overexpression in hippocampal CA1–CA3 glutamatergic neurons in a rodent model led to decreased AEA level in hippocampus, and resulted in anxiety-like behavior." (PMID 32316328, 2020). "These brain regions were chosen because FAAH and the CB1 receptor are highly expressed in these regions, which are known to regulate alcohol-reward related behavior and fear- and anxiety-related behavior." (PMID 31561480, 2019). "FAAH genetic variation also impacts enzyme expression and activity, thereby increasing AEA levels and attenuating anxiety-like behaviors in both mice and humans." (PMID 30279403, 2018). "Pretreatment with the FAAH inhibitor, URB597, or MAGL inhibitor, JZL184, which enhanced endogenous levels of AEA and 2-AG, respectively, significantly attenuated CUS-induced anxiety-related behavior in the light-dark box and concurrent thermal hyperalgesia." (PMID 26342110, 2015). "Here, we have reported that ST4070, through the inhibition of FAAH activity, elevates AEA levels in brain regions critically involved in the control of anxiety and stress response, such as frontal cortex and dorsal striatum." (PMID 26360704, 2015). "Hippocampus is a brain structure with an important role in the modulation of anxiety-related behaviors and a high density of CB1 and TRPV1 receptors and FAAH enzyme exist in this area." (PMID 23493622, 2012). "Since cannabidiol (CBD) does not act directly on CB1R, but rather as a hydrolyzer of fatty acid amide hydrolase (FAAH) which is the membrane enzyme hydrolyzing AEA, it could potentially reduce anxiety." (PMID 40806746, 2025). "To summarize, Nex-FAAH-KO mice lacking FAAH in cortical glutamatergic neurons show a tendency for increased anxiety-like behavior after CSD." (PMID 41310892, 2025). "FAAH and MAGL inhibitors target inflammation and anxiety in AD." (PMID 38612861, 2024). "FAAH/MAGL inhibitor’s applications relating to learning and memory, neuropathic pain, anti-inflammatory, analgesic, improving synaptic plasticity, depression, anxiety, and other processes have been evaluated." (PMID 38612861, 2024). "In a study, a single injection of the FAAH blocker URB597 improved unpleasant memory and anxiety-like behavior in Fmr1-deficient mice without impairing their social behavior." (PMID 38744725, 2024). "Taken together, this suggested that FAAH inhibition has no specific effect on anxiety but abolishes the anxiogenic effects of aversive environments." (PMID 37958761, 2023). "In support of the involvement of stress, a modified—more stressful—version of the elevated plus maze test revealed anxiolytic effects in a study where FAAH inhibition did not affect anxiety under normal conditions." (PMID 37958761, 2023). "Modulatory effects in the cannabinoid system through the inhibition of the activities of the fatty acid amide hydrolase (FAAH) and the monoacylglycerol lipase (MAGL) enzymes may serve as therapeutic potentials in treating disorders such as mood and anxiety." (PMID 37111813, 2023). "Increasing anandamide levels via pharmacological inhibition of its degrading enzyme, fatty acid amide hydrolase (FAAH), or genetic deletion of FAAH elicits phenotypes that are prominent for decreased anxiety-like behavior, as we observed in our evaluation of SGIP1−/− mice." (PMID 37547151, 2023).
Anxiety (continued). "Indeed, the FAAH inhibitor URB597, directly injected in rat prefrontal cortex, reduces anxiety-like behaviors at low doses." (PMID 35159280, 2022). "Inhibition of FAAH can prevent stress-induced increases in glutamate release in the BLA, and local blockade of FAAH within the BLA can blunt stress-induced activation of the HPA axis, anxiety-like behavior, and fear extinction impairments." (PMID 34598785, 2022). "In the PF-04457845 study reviewed above, 10 days of FAAH inhibition produced no detectable effects on baseline mood or anxiety." (PMID 34598785, 2022). "As increased FAAH activity was found to contribute to the generation of colitis-induced anxiety, and given previous work that showed that activation of CRF-R1 can induce FAAH hydrolysis of AEA during psychological stress, we examined CRF signaling as a potential upstream mechanism in our model." (PMID 33452437, 2021). "In contrast to the lack of effect of FAAH inhibition, the present data demonstrate that increasing 2-AG tone augments anxiety-like behaviour of VPA-exposed females in the EPM and OFT." (PMID 34207178, 2021). "FAAH is needed for AEA reuptake and metabolism, and FAAH inhibitors are suggested to increase synaptic AEA leading to beneficial therapeutic effects in models of chronic pain, anxiety, or depression." (PMID 34572359, 2021). "The FAAH/MAGL inhibitor at the 3 mg/kg dose did not influence the locomotion or other anxiety-like behavior changes induced by NTG, nor did it affect these activities when used alone (NTG vehicle), confirming previous data." (PMID 34685523, 2021). "More specifically, we evaluated the effect of JZL195, an FAAH/MAGL inhibitor, on (i) NTG-induced trigeminal hyperalgesia at the orofacial formalin test; (ii) anxiety-like behavior and spontaneous locomotor activity; and (iii) molecular mediators of the potential JZL195 anti-migraine effect." (PMID 34685523, 2021). "It is possible, then, that the publications included in this review found differences in FAAH related to anxiety-like behavior but not depressive-like behavior." (PMID 33494322, 2021). "Studies have related depression and anxiety to the expression and/or functionality of cannabinoid type 1 (CB1) receptors and FAAH in brain areas belonging to the amygdala-hippocampal-corticostriatal neural circuit, especially the frontal cortex in depression and the amygdala in anxiety disorders." (PMID 32595741, 2020). "Indeed, stress exposure induces anxiety-like behavior and reduces AEA brain levels by increasing FAAH activity in the Amy, a brain region closely involved in AEA-mediated emotional regulation." (PMID 32395111, 2020). "The blockade of FAAH and MAGL enzymatic activity is considered a therapeutic target for neuropathic pain relief and may also alleviate inflammatory bowel diseases, anxiety, cancer metastasis, and Alzheimer's diseases." (PMID 32508955, 2020). "Another study revealed that the FAAH inhibitor (PF-3845) reduced marble burying behavior (predictive of stress and anxiety) at doses that did not alter locomotion." (PMID 33066366, 2020). "Specifically, inhibition of the eCB‐degrading enzyme FAAH has been successfully tested in animal models for inflammation, chronic pain, and anxiety, without remarkable adverse effects." (PMID 33016621, 2020). "We then investigated whether impaired AEA signaling in FAAH-overexpressing mice leads to alterations of endocannabinoid-regulated synaptic plasticity (LTP, LTD, DSE, DSI), emotional responses (anxiety, stress coping) and memory processes." (PMID 30532004, 2019). "Thus, in this study we explored the comparative effects of FAAH, MAGL and dual FAAH/MAGL inhibitors on anxiety-like behaviors, locomotor activity, body temperature and cognitive functions." (PMID 29695817, 2018). "Overall, we propose that the profile of FAAH activity and AEA levels in different anxiety-relevant brain regions may change time-dependently, in order to provide an appropriate response to a certain type of conflict." (PMID 26360704, 2015).
Anxiety (continued). "Much alike other peripherally administered FAAH inhibitors, oral ST4070 effectively reached its pharmacological target in the central nervous system, where it was able to produce a consistent inhibition of FAAH activity within anxiety-relevant brain regions." (PMID 26360704, 2015). "FAAH inhibitors are promising pharmacological agents in the treatment of pain and anxiety without drug-seeking side effects." (PMID 22776995, 2012). "This review consolidates recent clinical evidence for FAAH inhibitors, examining their influence on AEA, safety and efficacy in ameliorating symptoms across a range of psychiatric conditions, including depression, anxiety, PTSD, and cannabis use disorder (CUD)." (PMID 42209468, 2026). "Recently, we demonstrated that abstinence from a highly palatable diet could promote anxiety-like behavior by inducing permanent changes in the expression of ECS in non-dopaminergic brain areas and that the treatment with the selective FAAH inhibitor PF-3845 reversed such effects." (PMID 39582223, 2025). "While significant sex differences in rs324420 genotype frequencies have not been found in elite athletes, it seems that oestrogens may modify emotional behaviour by dysregulating the FAAH enzyme, increasing the ECS signalling and, as a result, decreasing women’s anxiety." (PMID 37895295, 2023). "A recent systematic review found that FAAH protein contributes to biological and clinical aspects of AUD and that pharmaceutical targeting of this molecule could be useful for alcohol withdrawal by reducing anxiety and resumption of alcohol intake." (PMID 37895295, 2023). "In this study we provide the first mechanistic insights into how the microdeletion identified in Patient PFS negatively affects FAAH expression and leads to pain insensitivity, accelerated wound healing and the lack of depression and anxiety symptoms observed in the patient." (PMID 37222214, 2023). "However, URB-597 did not affect anxiety in several studies; in addition, FAAH-KO mice were not different from controls in another." (PMID 37958761, 2023). "As opposed to this, FAAH inhibition lessens anxiety-like behavior and may promote an antidepressant impact via stimulation of the CB1 receptor." (PMID 37372343, 2023). "Drugs that inhibit the cellular uptake and/metabolism of cannabinoids such as fatty acid amide hydrolase (FAAH) and monoacylglycerol lipase (MAGL) may have benefits against diseases/disorders such as cancer, anxiety, neuropathic path, and inflammatory bowel disease." (PMID 34502379, 2021). "Increasing anandamide levels via chemical inhibition of its catabolic enzyme fatty acid amide hydrolase (FAAH) or the deletion of FAAH resulted in phenotypes with behavioural aberrations including decreased anxiety‐like behaviour, as we observed in the present tests with SGIP1−/− mice." (PMID 33491188, 2021). "For example, eCB is downregulated in numerous models of fear-, depression-, anxiety-, and trauma-related disorders, and inhibiting the synthesis of eCB by overexpressing FAAH significantly increases sensitivity to negative emotions, contextual fear memory, loss of interest, etc.." (PMID 34950028, 2021). "Rodent studies suggest beneficial effects of ECB signaling enhancers such as the FAAH inhibitor URB597 (URB; FAAH degrades AEA), the CB1/2 receptor agonist WIN55,212-2 (WIN), and cannabidiol (CBD; a cannabis sativa constituent) in rodent models for depression, anxiety, and PTSD." (PMID 33450928, 2021). "Yet, FAAH overexpression in BLA pyramidal neurons can also attenuate stress and anxiety-like behaviors: as an explanation, FAAH overexpression could dry out tonic anandamide signaling at GABAergic synapses and shift the excitation/inhibition balance towards inhibition of BLA output neurons." (PMID 32848597, 2020). "Furthermore, we show that the prosocial action of FAAH inhibition is independent of reducing anxiety in BTBR mice." (PMID 28861483, 2016).
Anxiety (continued). "FAAH activity and eCB content in specific brain regions related to emotionality, motivation and behavioural planning (hippocampus, striatum and frontal cortex) were also assessed, in order to better understand the neurobiological mechanisms through which ST4070 acts to modulate anxiety." (PMID 26360704, 2015). "Notably, FAAH did not directly predict anxiety symptoms in this preadolescent sample." (PMID 40639419, 2025). "Modulating the eCBome–GM–brain axis with inhibitors of fatty acid amide hydrolase (FAAH), transient receptor potential vanilloid 1, and monoacylglycerol lipase (MAGL) may improve repetitive, stereotypical, and sensory behaviors, and alleviate sociability impairments, depression and anxiety." (PMID 40605060, 2025). "In addition, the injection of the FAAH inhibitor, URB597, normalized the upregulation of CB1r in the CA1 of Hipp and BLA of rats exposed to a shock and reminder model of PTSD and attenuated startle response and anxiety-like behavior in a predator exposure animal model of PTSD." (PMID 32395111, 2020). "Similarly, while FAAH has been shown to be elevated in animal models of anxiety in previous studies, the lack of correlation between [11C]CURB λk3 and anxiety in the MDD group may suggest that FAAH does not correspond to the anxiety associated with MDD in humans." (PMID 40550956, 2025). "Sex- and disease-dependent effects have been reported for FAAH enzyme inhibitors (e.g., PF3845, URB597) in vivo, including producing anti-anxiety effects under stressful conditions without affecting control animals, and improving cognitive function in male but not female rats." (PMID 35269478, 2022). "Moreover, we revealed that an acute administration of only FAAH inhibitor URB 597 (0.3 mg/kg) had an anxiolytic effect, while MAGL inhibitor JZL 184 (at any used doses (2–40 mg/kg)) after an acute injection had no influence on anxiety behavior in mice, as observed in the EPM test." (PMID 40005177, 2025).